DISC1 (DISC1 scaffold protein)
Diseases named in the same sentence as DISC1 in open-access papers (continued):
Sharing a sentence is not in itself a finding about the gene and the disease.
substance abuse (1 paper, 2019). The use of a drug for a reason other than which it was intended or in a manner or in quantities other than directed. "The effects of DISC1-deficiency on the elevation of D1R and cocaine-induced behaviors might be in line with the comorbidity between substance abuse and other psychiatric disorders." (PMID 30915712, 2019).
substance dependence (1 paper, 2019). The psychological or physiological need to take a substance in order to experience its effects or to avoid the effects of its absence. "Collectively, our results suggest that DISC1 is relevant to the interface among substance dependence and other psychiatric conditions." (PMID 30915712, 2019).
psychiatric disorder (133 papers, 2008 to 2026). A disorder characterized by behavioral and/or psychological abnormalities, often accompanied by physical symptoms. "The DISC1 gene was originally identified in a large family, where it was strongly linked to the presence of major mental illnesses, including schizophrenia (SCZ)." (PMID 39194719, 2024). "Previous studies have established that DISC1 has been extensively studied as a genetic risk factor for mental illnesses." (PMID 38920990, 2024). "This is particularly important, as mental illnesses associated with DISC1 show oxidative stress phenotypes." (PMID 39194719, 2024). "In this context, DISC1 has been proven to act in a cell type- and context-dependent fashion, relevant to the neural development and integration of psychiatric disease risk factors within a set of defined molecular functions." (PMID 36831241, 2023). "Despite the nomenclature, the gene Disrupted In Schizophrenia 1 (DISC1) confers risk for all mental illnesses." (PMID 37759960, 2023). "The C-terminal domain harbors several mutations that are linked to increased risks of mental illness, including the polymorphism S704C and a frameshift mutation downstream of L807 that leads to pathological aggregation of DISC1." (PMID 38192336, 2023). "DISC1 C-terminal domain is especially relevant from a pathophysiological perspective because it encompasses polymorphisms recognized as risk factors for mental illness, such as the S704C and L807-frameshift mutant." (PMID 38192336, 2023). "A gene known as the Disrupted-In-Schizophrenia-1 (DISC1) gene can be altered by a translocation and is associated with several psychiatric disorders." (PMID 36923289, 2023). "Subsequent studies have shown that several genetic variations of DISC1 are linked to increased risks of mental disorders and neuronal diseases." (PMID 38192336, 2023). "Among the genetic factors associated with schizophrenia, the DISC1 gene is a genetic risk factor for major mental illness." (PMID 34071723, 2021). "Perturbation of the multifunctional scaffolding protein DISC1 is linked to a range of behavioral phenotypes that are associated with major psychiatric disorders." (PMID 32029441, 2020). "The elegant use of complementary isogenic iPSC lines strongly supports this conclusion and suggests that deleterious DISC1 mutations are a defining cause in synaptic pathology in patients with major psychiatric disorders." (PMID 32033412, 2020). "A series of interesting studies were conducted using iPSC-derived forebrain neurons obtained from donors affected from a familial form of SCZ and major psychiatric disorders that co-segregate with a mutation of the disrupted-in-schizophrenia-1 (DISC1) gene." (PMID 32625059, 2020). "Some of them relate to DISC1 mutations, which have been identified as a high-risk genetic factor for a wide range of psychiatric disorders including SCZ and ASD." (PMID 33308283, 2020). "Disrupted-in-Schizophrenia 1 (DISC1) is a candidate gene implicated in multiple major psychiatric disorders including SCZ, BD and MDD." (PMID 33981965, 2019). "We show levels of Disrupted‐in‐schizophrenia‐1 (DISC1), which is genetically associated with psychiatric disorders and AD, decrease in the brains of AD patients and transgenic model mice and in Aβ‐treated cultured cells." (PMID 30488644, 2019). "Disrupted‐in‐schizophrenia‐1 (DISC1) is a genetic risk factor for various psychiatric disorders including schizophrenia, major depression, and bipolar disorders." (PMID 30488644, 2019). "Genetic analyses of patients with psychiatric disorders have identified additional mutations in DISC1 pathway genes." (PMID 33981965, 2019). "In an American family with mental illness, a frame shift mutation following amino acid 807 in the DISC1 protein was reported." (PMID 29324815, 2018).
psychiatric disorder (continued). "Ming & Song's group have since generated hiPSCs from four members of an American family in which a frameshift mutation of DISC1 co-segregated with major psychiatric disorders and furthermore produced different isogenic iPS cell lines via gene editing." (PMID 29352035, 2018). "Studies further verified the potential association of the DISC1 gene with mental illnesses, especially schizophrenia, because many variants and polymorphisms of DISC1 were found in persons with schizophrenia." (PMID 30233327, 2018). "Here, we utilize human iPSCs harboring distinct mutations in DISC1 that have been found in families with major mental illness." (PMID 30410030, 2018). "In both human and mouse cells, DISC1 variants associated with mental illness reduce NPC proliferation and affect responses to WNT12." (PMID 29643329, 2018). "The association of DISC1 gene with major mental illness has been confirmed and replicated in numerous independent genetic studies." (PMID 29156684, 2017). "Here we have demonstrated that variations within the NDE1 locus, encoding a protein of the DISC1 network of protein interaction partners, can affect both gene expression levels and medication usage of psychoactive drugs used to treat major mental illnesses." (PMID 29142105, 2017). "They reported that variations in DISC1 were most significantly associated with cortical thinning in regions often implicated in psychiatric disorders." (PMID 26301809, 2015). "More than two decades ago, DISC1 has been identified as a major genetic risk factor involved in psychiatric disorders." (PMID 25735038, 2015). "The involvement of the DISC1 pathway in psychiatric disorders has since been reported in genetic association studies within different pedigrees and more diverse populations." (PMID 26301809, 2015). "The relevance of the Disc1tr Hemi model to other forms of DISC1 mutations associated with psychiatric disease, such as missense mutations in the gene, should also be interpreted with some caution." (PMID 25989143, 2015). "Since its discovery in 2000, DISRUPTED-IN-SCHIZOPHRENIA (DISC1) has been one of the most widely studied genetic risk factors for mental illness." (PMID 26405049, 2015). "DISC1 has since been implicated in several psychiatric disorders, including autism spectrum disorders, and cognitive functions such as sustained attention and visual working memory." (PMID 26649006, 2015). "More than a decade after the first description of DISC1 as a susceptibility gene for major psychiatric disorders, multiple studies attempted to trace its potential functions during brain development." (PMID 25071449, 2014). "Recently Disrupted-in-Schizophrenia-1 (DISC1) and many other genes implicated in psychiatric disorders were found to have effects on primary cilia when knocked down in vitro." (PMID 25184295, 2014). "Here we review a group of studies that utilize mouse models of DISC1, a susceptibility gene for psychiatric disorders, to examine the interaction between genetic and environmental risk factors." (PMID 24027503, 2013). "Further support for a possible sex-specific effect of the DISC1 pathway in conferring risk for mental illness, also comes from animal studies." (PMID 23637818, 2013). "Mutations in DISC1 are strongly associated with psychiatric disorders, such as schizophrenia, major depression, bipolar disorder, and autism." (PMID 25364642, 2012). "The observation of both physical and functional interactions among this group of four proteins that share common biological functions makes them an attractive target for investigating the mechanisms that underlie DISC1-associated psychiatric disorders." (PMID 25364642, 2012). "Disrupted-In-Schizophrenia-1(DISC1) is a risk gene for schizophrenia and other mental illnesses, encoding a scaffold protein that is critical for adult neurogenesis, neuronal migration, dendrite maturation and synaptogenesis." (PMID 23272119, 2012).
psychiatric disorder (continued). "Disrupted-in-Schizophrenia 1 (DISC1) is a prominent susceptibility gene for major psychiatric disorders." (PMID 22792496, 2012). "Disrupted-In-Schizophrenia-1 (DISC1) is a susceptibility gene for schizophrenia and other psychiatric disorders." (PMID 23272119, 2012). "The involvement of DISC1 in conferring increased risk of schizophrenia and other major psychiatric disorders has since been confirmed by numerous association and linkage studies in multiple populations (reviewed)." (PMID 19000741, 2009). "Even with the limitation of KO modeling, DISC1 KO mice may recapitulate some of the functional milestones associated with psychiatric disorders." (PMID 36831241, 2023). "Interestingly, DISC1 loss-of-function mutations have been associated with psychiatric disorders associated with altered neuronal morphology." (PMID 37306762, 2023). "Oxidative stress and mitochondrial deficiency occur in several psychiatric disorders and might be the result of DISC1 dysfunction." (PMID 36012679, 2022). "The DISC1 is a robust susceptibility gene for psychiatric disorders, including SCZSD." (PMID 34462417, 2021). "SLC1A7 and DISC1 are also susceptibility genes for mental illnesses." (PMID 33568133, 2021). "Disrupted-in-schizophrenia-1 (Disc1) is a susceptibility gene for major psychiatric disorders." (PMID 29374282, 2018). "One mutation was engineered to mimic the consequences on DISC1 protein of a balanced translocation linked to mental illness in a Scottish pedigree; the other mutation was identified in an American pedigree with a high incidence of mental illness." (PMID 30410030, 2018). "DISC1 has been implicated in psychiatric disease based on genetic studies, including its interruption by a balanced translocation that increases the risk of major mental illness." (PMID 29643329, 2018). "The idea that such protein interaction partners of DISC1 are encoded for by genes which show genetic interaction in mental illness is termed the DISC1 network hypothesis." (PMID 29142105, 2017). "The gene Disrupted in Schizophrenia-1 (DISC1) is linked to a range of psychiatric disorders." (PMID 28720848, 2017). "DISC1 is the prototypical example of a gene associated with several major psychiatric disorders." (PMID 27378904, 2016). "Thus, DISC1 is a major susceptibility factor for mental illness and a relevant genetic entry point to identify core endophenotypes implicated in neuropsychiatric disorders." (PMID 27378904, 2016). "Consistent with a disease mechanism based on DISC1 loss-of-function, DISC1 expression is also attenuated in human induced pluripotent stem (iPS) cells derived from members of a family with a DISC1 frame-shift mutation that co-segregates with major psychiatric disorders." (PMID 27378904, 2016). "Considerable evidence implicates DISC1 as a susceptibility gene for multiple psychiatric diseases." (PMID 25989143, 2015). "Presumably due to DISC1 being one of the most established risk genes for psychiatric disorders, its clear involvement in brain development, and the availability of many mouse models, more G × E studies have been performed using DISC1 mouse models than with any other risk gene." (PMID 24027503, 2013). "This hypothesis proposes that in addition to disruption of DISC1, the disruption of other genes in the pathways DISC1 is involved in could also increase risk to mental illness." (PMID 22363459, 2012). "Meanwhile, investigations into function of DISC1 have revealed that it may contribute to risk for psychiatric disorders through its effects on the processes of neurodevelopment." (PMID 21569632, 2011). "Thus, truncation of DISC1 constitutes one of the largest known risk factors for mental illness." (PMID 25735038, 2015). "Overall, DISC1 dysfunction may cause impaired differentiation of oligodendrocytes by affecting Sox10 and/or Nkx2.2 expression and consequently contribute to the pathophysiology of psychiatric disorders." (PMID 25705664, 2015).
psychiatric disorder (continued). "Therefore, the study of DISC1 biology may provide fundamental insight into the complex interplay between genetic, developmental and environmental factors that underlie mental illness." (PMID 26405049, 2015). "However, it is possible that the underlying pathogeneses of DISC1 for different psychiatric disorders might be different." (PMID 21569632, 2011). "In this regard, preclinical studies identified a binding region between DISC1 and ATF4 in the genomic locus of PDE4D, a gene implicated in psychiatric disorders." (PMID 36831241, 2023). "Studies show that NDE1 is aberrantly expressed in neurological and psychiatric disorders, and binds to DISC1 to mediate the latter’s role in neurogenesis and neural development." (PMID 34981809, 2022). "The second part of the review addresses the known proteins whose aggregation in brain tissue has been observed in psychiatric disorders (amyloid, tau protein, α-synuclein, DISC-1, disbindin-1, CRMP1, SNAP25, TRIOBP, NPAS3, GluA1, FABP, and ankyrin-G)." (PMID 36430976, 2022). "Disrupted-in-schizophrenia 1 (DISC1) was first identified in a large Scottish family with a high loading of major mental illness." (PMID 36590092, 2022). "Although the genetic association of DISC1 with the various psychiatric conditions is still to be further clarified, the identification of DISC1 as a novel regulator of the molecular clock may suggest its role in the interface between some aspects of psychiatric disorders and the circadian system." (PMID 33542182, 2021). "We demonstrate that reduced DISC1 expression, a key molecular candidate to study biology relevant to behavioral constructs related to several psychiatric disorders, leads to elevated E-I balance in the MD–mPFC thalamofrontal circuit." (PMID 32029441, 2020). "Several research groups have generated animal models of Disc1 to study the unique molecular signature of psychiatric disease that arises from this genetic locus." (PMID 32102223, 2020). "Towards these ends, several groups have generated animal models of Disc1 towards understanding the unique molecular neuropathogenesis of psychiatric disease that arises from this genetic locus." (PMID 30745562, 2019). "This concept was underpinned by the function of the molecule disrupted-in-schizophrenia 1 (DISC1), which represents an intracellular hub of developmental processes and has been related to cognitive dysfunction in psychiatric disorders." (PMID 30617212, 2019). "This study thus uncovers a new mechanism for DISC1 as a major hub protein at the crossroads of neurodevelopment, neuronal signaling and psychiatric disorders." (PMID 29937727, 2018). "DISC1 was first isolated by cloning the breakpoints of a 1 : 11 balanced translocation co-segregating with major psychiatric disorders in a large Scottish pedigree." (PMID 29352035, 2018). "This genomic region contains the coding genes translin-associated factor X (TSNAX) and DISC1, and the lncRNA DISC2, all of them previously associated with psychiatric disorders." (PMID 29751665, 2018). "Further evidence supporting the involvement of DISC1 in mental disorders has been more recently debated." (PMID 29352035, 2018). "Direct disruption of DISC1 impacts on neurodevelopment, glutamate-signalling, cognitive ability and liability to psychiatric disorder." (PMID 29880880, 2018). "The role of DISC1 in psychiatric disorders remains controversial; however, many biological studies have shown that DISC1 plays important roles in cortical development." (PMID 27847649, 2016). "Collectively, these results show that DISC1-dependent enhancement of SV exocytosis is mediated by Cav2.2 and point to aberrant glutamate release as a probable endophenotype of major psychiatric disorders." (PMID 27378904, 2016).